CERS3 (ceramide synthase 3)
Description:
Ceramide synthase that catalyzes the transfer of the acyl chain from acyl-CoA to a sphingoid base, with high selectivity toward very- and ultra-long-chain fatty acyl-CoA (chain length greater than C22). N-acylates sphinganine and sphingosine bases to form dihydroceramides and ceramides in de novo synthesis and salvage pathways, respectively. It is crucial for the synthesis of ultra-long-chain ceramides in the epidermis, to maintain epidermal lipid homeostasis and terminal differentiation.
Synonyms: LASS3; MGC27091; ARCI9
Tractability: Antibody: UniProt predicts a signal peptide or a membrane-spanning region.
Gene: Protein-coding gene on chromosome 15 (100,400,395 to 100,544,995, reverse strand). Ensembl gene ENSG00000154227.
Subcellular location: Endoplasmic reticulum membrane
Subcellular location (Human Protein Atlas): Nucleoplasm
Pathways (Reactome):
Metabolism: Sphingolipid de novo biosynthesis
Gene Ontology:
Molecular function: protein binding; sphingosine N-acyltransferase activity; DNA binding
Biological process: ceramide biosynthetic process; keratinocyte differentiation; cornification; epidermis development; sphingolipid biosynthetic process; sphingolipid metabolic process
Cellular component: nucleoplasm; endoplasmic reticulum; endoplasmic reticulum membrane; membrane
Genetic constraint (gnomAD): Loss-of-function variants: 25 observed, 30.62 expected, observed/expected ratio (o/e) 0.82, 90% interval 0.59 to 1.14. The upper end of that interval is the gene's LOEUF score, 1.14, which puts it in group 4 of 6, group 1 being the genes least tolerant of losing a copy. Missense variants: 341 observed, 342.26 expected, observed/expected ratio (o/e) 1, 90% interval 0.91 to 1.09. Synonymous variants: 136 observed, 116.85 expected, observed/expected ratio (o/e) 1.16, 90% interval 1.01 to 1.34.
Homologues: Orthologues: chimpanzee CERS3 (99% identical), macaque CERS3 (96% identical), pig CERS3 (86% identical), rabbit CERS3 (80% identical), dog CERS3 (80% identical), mouse Cers3 (78% identical), rat Cers3 (78% identical), zebrafish cers3a (51% identical), zebrafish cers3b (46% identical), tropical clawed frog cers3 (44% identical), Drosophila melanogaster schlank (35% identical), Caenorhabditis elegans hyl-1 (26% identical), and 1 more. Paralogues in human: CERS2 (51% identical), CERS4 (44% identical), CERS5 (40% identical), CERS6 (39% identical), CERS1 (21% identical).
Diseases named in the same sentence as CERS3 in open-access papers:
CERS3 is named in the same sentence as 44 diseases in open-access papers, as found by Europe PMC text mining. Sharing a sentence is not in itself a finding about the gene and the disease. The quoted sentences say what the papers report.
ichthyosis (18 papers, 2013 to 2025). Disorders of cornification that are characterized by visible scaling and/or hyperkeratosis of most or all of the skin. "Deficiencies or dysregulation of CerS3 have been linked to severe skin disorders, including congenital ichthyosis (characterized by impaired barrier function and excessive dryness), whereas functional loss of CerS3 causes lethal skin barrier disruption." (PMID 41465291, 2025). "Numerous loss-of-function mutations in CerSs have been described, including two mutations of Trp residues [W15R and W10M in CerS3], which cause ichthyosis characterized by impairment of epidermal barrier function." (PMID 39653242, 2024). "Accordingly, humans carrying mutant alleles of ELOVL4, CYP4F22, or CERS3 develop a similar ichthyosis pathology as reported for ABHD5 and PNPLA1 deficiency due to the lack of ULC ω-hydroxy ceramides and AcylCer in the epidermis." (PMID 30361410, 2018). "A mutation in CERS3 is responsible of autosomal recessive congenital ichthyosis, and interestingly, scleroderma-like changes have been described in different clinical variants of ichthyosis." (PMID 28861129, 2017). "In this way, we were able to characterize a new type of ichthyosis and to provide evidence for the involvement of CERS3 mutations in the development of ARCI in humans." (PMID 23754960, 2013). "To investigate the role of CERS3 mutations in the development of ichthyosis we performed histological and biochemical studies using a skin sample of patient H carrying the splice site mutation in the CERS3 gene." (PMID 23754960, 2013). "For example, the genes which increased most in hubness in the two skin tissues were APOE, which has been linked with skin lesions known as xanthomas (although it is more famous because of its link with Alzheimer’s) and CERS3, which when mutated causes congenital ichthyosis, a skin disease." (PMID 25970446, 2015). "Thus, we conclude that the patients' ichthyosis skin phenotype results from mutations in CERS3 that significantly impair the epidermal ceramide synthesis, in particular the synthesis of (glucosyl)acylceramides." (PMID 23754960, 2013). "We also identified a homozygous deletion in exon 13 of CERS3 gene in a 15-year old patient (E1) affected with syndromic ichthyosis (CIE with ocular defect)." (PMID 34983512, 2022). "An autosomal recessive mutation leading to the inactivation of CerS3 was also reported to result in congenital ichthyosis, further highlighting the importance of CerS3 and the synthesis of ultra-long ceramides in maintaining skin physiology." (PMID 36077094, 2022). "Large decreases in or loss of acylceramide due to mutations in the genes involved in acylceramide synthesis (such as CERS3, CYP4F22 and ELOVL4) causes non-syndromic ARCI (CERS3 and CYP4F22) or a syndromic form of ichthyosis (ELOVL4) (refs 5, 8, 10, 12, 21)." (PMID 28248318, 2017). "Therefore, the loss of ceramides and sulfated cholesterol owing to deficiencies in CerS2, CerS3 and SULT2B1 is implicated in not only the reduction of barrier function but also the pathogenesis of skin diseases such as psoriasis and ichthyosis." (PMID 40637102, 2025). "Delexon13 in CERS3 was reported in a patient with syndromic ichthyosis." (PMID 34983512, 2022). "However, the present ichthyosis skin phenotype of our patients has never been reported in WM-like syndrome patients, suggesting that mutations in FLJ42289 and/or CERS3 (ceramide synthase 3) could be associated with this unusual form of ARCI." (PMID 23754960, 2013).
autosomal recessive congenital ichthyosis (10 papers, 2013 to 2023). Autosomal recessive form of inherited ichthyosis. "A more recent study detailed lipid profile changes and alterations in keratinocyte differentiation in patients with autosomal recessive congenital ichthyosis with mutations in the ceramide synthase 3 (CerS3) gene." (PMID 32843345, 2020). "Mutations in CERS3 cause autosomal recessive congenital ichthyosis." (PMID 36441023, 2022). "Mutation of CerS3 has been reported as a reason for autosomal recessive congenital ichthyosis (ARCI), a keratinization disorder." (PMID 37760612, 2023).
psoriasis (6 papers, 2019 to 2025). An autoimmune condition characterized by red, well-delineated plaques with silvery scales that are usually on the extensor surfaces and scalp. "For example, the ceramide abundances in psoriasis lesional skin matched the increased expression of CERS3 and SPTLC2 and the decreased expression CERS6." (PMID 35900871, 2022). "Then, the levels of ceramides and glucosylceramides, as well as the protein expression of ELOVLs and CerS3, in the lesional skin of patients with psoriasis and healthy volunteers were investigated." (PMID 32316273, 2020). "GE significantly increased the CERS3 expression in GE treated HPKs and psoriasis-like HPKs compared to untreated cells." (PMID 32316273, 2020). "The expression of CerS3 increased slightly in AD-like dermatitis, but it increased by 4.6-fold in psoriasis-like dermatitis." (PMID 30838224, 2019). "Stimulating the expression of ELOVL1 or 4 and CERS3 might be beneficial for psoriasis patients with an increased IFN-γ production." (PMID 32316273, 2020). "Our findings suggest that topical treatment with GE, which partly rescues the ELOVL4 downregulation in psoriasis-like HPKs and increases the CERS3 expression, might contribute to the prevention and/or treatment of psoriasis." (PMID 32316273, 2020). "We incubated normal HPKs and psoriasis-HPKs with GE and determined the CERS3 and ELOVL4 expression." (PMID 32316273, 2020). "We then analyzed the effect of GE treatment on CERS3 expression in HPKs and psoriasis-like HPKs." (PMID 32316273, 2020). "Thus, using drugs that stimulate the expression of ELOVLs and CERS3 could be beneficial for patients with psoriasis." (PMID 32316273, 2020). "A psoriasis mouse model showed decreases in the expression of fatty acid elongases ELOVL1, ELOVL3, and ELOVL4 as well as ceramide synthase 3, which are all involved in the synthesis of ceramides exceeding 24 carbons." (PMID 38992724, 2024). "The expression of ceramide synthase 3 (CERS3) and elongases (ELOVL1 and 4) was reduced in psoriasis lesions compared to healthy skin." (PMID 32316273, 2020). "Tawada and colleagues also showed that ELOVL4 and ceramide synthase 3 (CERS3) expression is decreased in IFN-γ stimulated keratinocytes and IFN-γ has been shown to be highly expressed in skin lesions of psoriasis patients and might be partially associated with barrier dysfunction in psoriasis." (PMID 32316273, 2020). "Finally, we generated psoriasis-like keratinocytes by treating HPKs with cytokines that are involved in the pathogenesis of psoriasis (IL-17, TNF-α, IL-22 and IFN-γ), and studied the effects of GE treatment on the expression of ELOVLs and CERS3." (PMID 32316273, 2020).
dermatitis (2 papers, 2019 to 2025). An inflammatory process affecting the skin. "In FAg-induced dermatitis, the expression of CerS1, CerS4, and CerS5 decreased, whereas the expression of CerS2 and CerS3 mildly increased with statistical significance." (PMID 30838224, 2019). "In particular, the mRNA expression of ELOVL1 and CerS3 increased significantly in IMQ-induced dermatitis." (PMID 30838224, 2019). "In IMQ-induced dermatitis, the expression of CerS1, CerS4, and CerS5 had a tendency to decrease, whereas the expression of CerS3 increased by 4.6-fold." (PMID 30838224, 2019). "Although the expression levels of CerS2 and CerS3, which prefer long-chain FAs as a substrate, were mildly elevated in FAg-induced dermatitis, those of CERs with long-chain FAs were decreased." (PMID 30838224, 2019).
ovarian carcinoma (2 papers, 2010 to 2021). A malignant neoplasm originating from the surface ovarian epithelium. "In addition, the carcinoma cells had greater expression of the mRNA's for two Cer synthases (CerS3 and 4) that produce very-long-chain-Cer, which were prevalent in the ST of most of the ovarian cancer samples." (PMID 20624317, 2010).
cholestasis (1 paper, 2025). Impairment of the bile flow caused by obstruction within the liver, or outside the liver in the bile duct system. "We found that enzymes contributing to CER production were upregulated by cholestasis, including DEGS2 in humans and Smpd3 and Cers3 in mice, indicating activation of CER generation by cholestasis." (PMID 40025008, 2025).
COVID-19 (1 paper, 2023). A disease caused by infection with severe acute respiratory syndrome coronavirus 2. "However, no significant regulation was observed in the gene expression of CERS1, CERS3, CERS5, and CERS6 within the same COVID-19 group." (PMID 37566018, 2023).
glioma (1 paper, 2023). A benign or malignant brain and spinal cord tumor that arises from glial cells (astrocytes, oligodendrocytes, ependymal cells). "On the other hand, CERS3 (Ceramide synthase 3) resides in a wide pocket of 9 proteins related to glioma, liver cancer, or both." (PMID 37743473, 2023).
Hypertension (1 paper, 2013). The presence of chronic increased pressure in the systemic arterial system. "Of the DEGs in the MCA that were altered by a single risk factor, hypertension alone vs. sham controls on a normal diet, FAM167A had the highest fold change, followed by CERS3 and FAM53C." (PMID 23874591, 2013). "Among the highly up-regulated genes in the MCA of the hypertension only group compared to sham controls were FAM167A, CERS3 and FAM53C." (PMID 23874591, 2013).
Insulin resistance (1 paper, 2016). Increased resistance towards insulin, that is, diminished effectiveness of insulin in reducing blood glucose levels. "In addition, upregulated CERS3 suggests an enhanced accumulation of ceramide which has previously been linked to insulin resistance." (PMID 27287443, 2016).
melanoma (1 paper, 2025). A malignant, usually aggressive tumor composed of atypical, neoplastic melanocytes. "The enrichment of these categories reflects the dysregulation of transcriptional programs typical of keratinocytes (e.g., SPRR1/2/3, KRT10/KRT16, LOR, IVL, EVPL, SCEL, TGM1/TGM3, CERS3, ACER1, DSP) and, above all, the epithelial crosstalk that influences melanoma biology." (PMID 41465101, 2025).
Obesity (1 paper, 2019). Accumulation of substantial excess body fat. "In addition, after bariatric surgery in subjects with obesity, the decrease in adipose tissue is accompanied by a reduction in CERS3 products." (PMID 31752434, 2019).
Palmoplantar keratoderma (1 paper, 2022). Abnormal thickening of the skin of the palms of the hands and the soles of the feet. "Our findings showed that palmoplantar keratoderma was associated with NIPAL4, TGM1, CYP4F22 mutations and CERS3 deletion, but with varying severity." (PMID 34983512, 2022).
rhegmatogenous retinal detachment (1 paper, 2019). Retinal detachment secondary to retinal tear or break. "For instance, a missense coding single-nucleotide polymorphism in CerS2 has been associated with rhegmatogenous retinal detachment, while mutations in CerS3 leading to impaired activity and expression of CerS3 have been linked to skin ichthyosis." (PMID 31632963, 2019).
sarcopenia (1 paper, 2024). Progressive decline in muscle mass due to aging which results in decreased functional capacity of muscles. "Then, ROC analysis was conducted to assess the diagnostic value of the target genes in sarcopenia, and the AUC values of CERS3, ADH1B, CYP26B1, and NNMT were greater than 0.7." (PMID 38838088, 2024).
skin cutaneous melanoma (1 paper, 2022). "Although the specific functions of CerS3 in cancer is unknown, and data from TCGA database indicates that CerS3 expression is decreased in human skin cutaneous melanoma." (PMID 35565311, 2022).
ulcerative colitis (1 paper, 2019). An inflammatory bowel disease involving the mucosal surface of the large intestine and rectum. "Also, in the dextran sodium salt (DSS) evoked model of ulcerative colitis, an increase in very long chain ceramides in CerS2 null mice was shown, accompanied by an increase in CerS3 mRNA expression." (PMID 30679689, 2019).
uterine cancer (1 paper, 2024). Primary or metastatic malignant neoplasm involving the uterine corpus and/or the cervix. "CERS3 is a signature gene in cervical cancer, but has no current relationship to uterine cancer, and TGIF1 additionally is considered a significantly mutated gene in cervical cancer." (PMID 38886487, 2024).
cancer (4 papers, 2010 to 2023). A tumor composed of atypical neoplastic, often pleomorphic cells that invade other tissues. "There are a lack of data on CerS3 expression in cancer, possibly due to a restricted expression of CerS3 in the mammalian body, the limited availability of specific antibodies, and the lethality of CerS3 knockout mice." (PMID 37760612, 2023). "In the IHC data of HPA, there is a lack of carcinoma or corresponding normal tissues of several candidate genes includingSDR9C7,RDH12,RAET1E,CERS3,PLA2G4E,CYP4F22, andDENND2C." (PMID 36017889, 2022).
infection (1 paper, 2025). The state of being infected such as from the introduction of a foreign agent such as serum, vaccine, antigenic substance or organism. "To understand their role in liver stage infection, we first assessed whether SPHK1 and CERS3 are involved in P. berghei invasion." (PMID 40689642, 2025). "In particular, depletion of CERS3 and SPHK1 affected PV size and infection rate, but not invasion." (PMID 40689642, 2025).
tumours (1 paper, 2022). "Other signature genes (TP63, CERS3, CSTA, CLCA2, DSC3 and DSG3) upregulated in C1 tumours are also markers of the squamous-like subtype, while further columnar-like marker genes (MUC5B and RGL3) are upregulated in C2 tumours." (PMID 36207323, 2022).
CERS3 also shares sentences with these, for which no sentence is quoted: congenital ichthyosis (7 papers); Bloom syndrome (2); deafness (2); adrenomyeloneuropathy (1); atopic dermatitis (1); autism (1); bladder carcinoma (1); brachydactyly (1); cyst (1); esophageal carcinoma (1); hereditary spastic paraplegia type 11 (1); Infertility (1); liver cancer (1); lung carcinoma (1); mantle cell lymphoma (1); neurodegenerative disease (1); osteoporosis (1); Prader-Willi syndrome (1); pustular psoriasis (1); schizophrenia (1); scleroderma (1); Tay-Sachs disease (1); xanthoma (1).